MCU (mitochondrial calcium uniporter)
Diseases named in the same sentence as MCU in open-access papers (continued):
Sharing a sentence is not in itself a finding about the gene and the disease.
endothelial dysfunction (2 papers, 2018 to 2020). In vascular diseases, endothelial dysfunction is a systemic pathological state of the endothelium (the inner lining of blood vessels) and can be broadly defined as an imbalance between vasodilating and vasoconstricting substances produced by (or acting on) the endothelium. "PTH determined mitochondrial calcium fluxes ([Ca2+]mt) and the mitochondrial calcium uniporter inhibitor Ru360 (10 μM) reduced mROS production and prevented the PTH-mediated endothelial dysfunction." (PMID 30662585, 2018). "Our study suggests that targeting the mitochondrial calcium uniporter components in ischemic vascular diseases does not confer sufficient protection against endothelial dysfunction." (PMID 33041854, 2020).
epilepsy (2 papers, 2018 to 2024). A brain disorder characterized by episodes of abnormally increased neuronal discharge resulting in transient episodes of sensory or motor neurological dysfunction, or psychic dysfunction. "To further evaluate the effects of MCU−/−ΔN as a potential therapeutic target in epilepsy, we additionally used an in vitro hyperexcitability model (low Mg2+ model) to test our hypothesis of potential protective MCU deficiency due to reduced ROS levels." (PMID 38652352, 2024). "Moreover, PTPRM, PPFIA1, SLC1A2, and SGCE were confirmed to be associated with epilepsy, while PTPRD, ASB5, and MCU were involved in neurological disorders." (PMID 29568349, 2018).
experimental autoimmune encephalomyelitis (2 papers, 2025). An autoimmune demyelinating disease of the central nervous system that is produced experimentally in animals by the injection of homogenized brain or spinal cord in Freund's adjuvant. "To evaluate the role of MCU in T-cell biology in vivo, we manipulated MCUa expression in primary rat effector T-cells by a CRISPR Cas9 gene editing approach and analysed their phenotype in an experimental autoimmune encephalomyelitis (EAE) model." (PMID 39623165, 2025).
fibrolamellar carcinoma (2 papers, 2025). "In fibrolamellar carcinoma (FLC), for example, MCU upregulation suppresses branched-chain amino acid degradation and the urea cycle by downregulating the transcription factor KLF15, facilitating anabolic metabolism over catabolism and further promoting tumor growth." (PMID 40724998, 2025).
Hearing impairment (2 papers, 2018 to 2021). A decreased magnitude of the sensory perception of sound. "In this study, we investigated MCU and NCLX in noise-induced hearing loss (NIHL) using adult CBA/J mice and noise-induced alterations of inner hair cell (IHC) synapses in MCU knockout mice." (PMID 30670946, 2018).
hyperglycaemia (2 papers, 2017 to 2019). "We propose that MCU is the critical protein responsible for mitochondrial Ca2+ overload in EC dysfunction caused by hyperglycaemia." (PMID 28777009, 2017). "To conclude, our study suggests that hyperglycaemia results in enhanced expression of MCU and MCUR1, leading to mitochondrial Ca2+ overload." (PMID 28777009, 2017). "Here, we demonstrate for the first time that hyperglycaemia-induced mitochondrial Ca2+ overload depends on MCU activation, leading to increased mitochondrial ROS levels and HUVEC dysfunction." (PMID 28777009, 2017). "The Ca2+ overload, heightened oxidative stress, increased apoptosis rate and decreased wound-healing ability induced by hyperglycaemia, and these effects were negated by MCU inhibition." (PMID 28777009, 2017). "Thus, our data provide evidence that melatonin is able to recover hyperglycemia-induced decrease of mitochondrial Ca2+ pools by increasing the expression of MCU." (PMID 31098384, 2019).
lung carcinoma (2 papers, 2023). "To assess whether tumor cell-intrinsic MCU affected antitumor immune responses, we generated Mcu deficient (Mcu−/−) MC38 murine colorectal tumor cells, Mcu−/− lewis lung carcinoma (LLC) murine lung cancer cells and Mcu−/− B16-OVA murine melanoma cells." (PMID 37502961, 2023).
lung fibrosis (2 papers, 2021 to 2022). "The mitochondrial calcium uniporter (MCU) regulates metabolic reprogramming in lung macrophages and the progression of pulmonary fibrosis." (PMID 34413485, 2022).
mesothelioma (2 papers, 2015 to 2019). A usually malignant and aggressive neoplasm of the mesothelium which is often associated with exposure to asbestos. "Mesothelioma cells with forced increases in the expression of MCU protein displayed elevated apoptotic activity." (PMID 26156019, 2015). "Based on these data, we investigated the MCU protein levels in normal and mesothelioma cells." (PMID 26156019, 2015). "Thus, having observed the critical dysregulation in overall Ca2+ handling and Ca2+-dependent apoptosis, we hypothesized that MCU could be affected in mesothelioma cells." (PMID 26156019, 2015). "As first, and similarly to the mesothelioma cell lines, we found that cells obtained from biopsies of MPM-affected patients displayed lower amounts of MCU protein than HMCs." (PMID 26156019, 2015). "Interestingly, treatments with NaV and high external [Ca2+] restore Ca2+ signaling and apoptosis without affecting MCU expression, demonstrating the significance of correct ER-mitochondrial Ca2+ cross-talk as a primary contributor to the apoptotic program in mesothelioma." (PMID 26156019, 2015).
muscular dystrophy (2 papers, 2022 to 2023). Muscular dystrophy (MD) refers to a group of more than 30 genetic diseases characterized by progressive weakness and degeneration of the skeletal muscles that control movement. "Here we show that the blockage of MCU‐1function by genetic or pharmacological modulation improves health in both aging C. elegans and C. elegans with muscular dystrophy." (PMID 36935171, 2023).
osteoporosis (2 papers, 2022 to 2026). A condition of reduced bone mass, with decreased cortical thickness and a decrease in the number and size of the trabeculae of cancellous bone (but normal chemical composition), resulting in increased fracture incidence. "Consistently, analysis of publicly available human datasets revealed age- and osteoporosis-associated downregulation of MCU expression in bone tissues." (PMID 42067615, 2026). "Our study is the first time to explore the role of the mitochondrial calcium uniporter (MCU) and its inhibitor ruthenium red (RR) in bone metabolism, clarifying the specific mechanism by which it inhibits osteoclast formation in vitro and plays a therapeutic role in osteoporosis in vivo." (PMID 36148414, 2022).
Parkinson disease (2 papers, 2019 to 2021). A progressive degenerative disorder of the central nervous system characterized by loss of dopamine producing neurons in the substantia nigra and the presence of Lewy bodies in the substantia nigra and locus coeruleus. "Inactivation of mitochondrial calcium uniporter reverses mitochondrial calcium overload and rescues dopaminergic neurons in our zebrafish models of Parkinson's disease." (PMID 31548178, 2019). "Notably, the inactivation of MCU has shown to be protective in neurons of Parkinson Disease zebrafish genetic model (namely in pink−/− fish), suggesting the crucial role of the MCU-dependent mitochondrial Ca2+ load on neuronal fitness." (PMID 34071006, 2021).
pulmonary arterial hypertension (2 papers, 2017 to 2021). Pulmonary arterial hypertension (PAH) is a group of diseases characterized by mean pulmonary artery pressure >20 mmHg and elevated pulmonary arterial resistance leading to right heart failure. "Furthermore, subsequent studies utilized anti-miR25 and anti-miR138 in pulmonary arterial hypertension (PAH) patients whose MCU expression is downregulated, and the final conclusion revealed the predictable overexpression of the MCU protein." (PMID 34307407, 2021).
steatosis (2 papers, 2023 to 2024). Increased lipid within the cytoplasm of cells. "But MCU expression is strikingly enhanced in patients with simple steatosis and steatohepatitis as well as in both livers and primary hepatocytes of murine models of MASH." (PMID 39523398, 2024).
acute pancreatitis (1 paper, 2020). An acute inflammatory process that leads to necrosis of the pancreatic parenchyma. "The primary aim of this study was to characterize the effect of MCU KO on the severity of experimental acute pancreatitis." (PMID 32516955, 2020). "The results of these experiments demonstrate that MCU knockout had no resolvable effect on the histopathological and biochemical parameters characterizing the severity of acute pancreatitis in the three experimental animal models of this disease." (PMID 32516955, 2020). "However, in three experimental models of acute pancreatitis (induced by caerulein, taurolithocholic acid 3-sulfate or palmitoleic acid plus ethanol), MCU knockout failed to reduce the biochemical and histological changes characterizing the severity of local and systemic damage." (PMID 32516955, 2020).
allergic disease (1 paper, 2023). An immune response that occurs following re-exposure to an innocuous antigen, and that requires the presence of existing antibodies against that antigen. "Some calcium signaling pathway-related genes, such as ERBB2, PDE1B, PDGFA, TPCN1, and MCU, have been reported to participate in the development of allergic diseases." (PMID 37328853, 2023).
breast invasive cancer (1 paper, 2021). "MCU, its dominant-negative form MCUb, LETM1, and VDAC, were found to be upregulated in breast invasive cancer." (PMID 33614647, 2021).
Cerebral ischemia (1 paper, 2021). Restriction of arterial blood supply to the brain associated with insufficient oxygenation to support the metabolic requirements of the tissue. "The existing evidence had clearly shown that Pyk2 modulates mitochondrial calcium uptake through phosphorylation of the MCU in cardiomyocyte, and the Pyk2/MCU pathway is activated in a rat cerebral ischemia model, which is responsible for mitochondrial dysfunction and neuronal apoptosis." (PMID 34026753, 2021). "In addition, in our previous study, we did find that the Pyk2/MCU pathway was activated in a rat cerebral ischemia model, which was responsible for mitochondrial dysfunction, calcium balance, and neuronal apoptosis." (PMID 34026753, 2021).
Chagas disease (1 paper, 2017). A parasitic infection caused by Trypanosoma cruzi. "Trypanosoma cruzi is the agent of Chagas disease, and the finding that this parasite possesses a mitochondrial calcium uniporter (TcMCU) with characteristics similar to that of mammalian mitochondria was fundamental for the discovery of the molecular nature of MCU in eukaryotes." (PMID 28487431, 2017).
clear cell renal cell carcinoma (1 paper, 2024). "EFHD1 was recently shown to bind MCU in clear cell renal cell carcinoma (ccRCC), and it therefore provides a great example of the predictive power of our resource." (PMID 39261663, 2024).
coronary atherosclerosis (1 paper, 2025). Atherosclerosis of the coronary vasculature. "Accumulating evidence suggests that the differential expression of MCU subunits can confer cardiovascular protection, attenuate cardiac cell death, and alleviate vascular inflammation and coronary atherosclerosis." (PMID 40422231, 2025).
cryptorchidism (1 paper, 2025). The failure of one or both testes of a male fetus to descend from the abdomen into the scrotum during the late part of pregnancy. "The results showed that six target proteins of TJP2, ZO-1, SYNPO2, SYNPO, LMCD1, and MCU showed characteristic distribution in the epididymal tissues of the cryptorchidism group and the normal control group." (PMID 41217791, 2025).
cystic fibrosis (1 paper, 2020). Autosomal recessive disorder caused by pathogenic variants in the CFTR gene (cystic fibrosis transmembrane conductance regulator), which encodes a chloride and bicarbonate channel expressed in epithelial cells, and follow the diagnosis criteria. "As an example, chronic stresses capable of increasing mitochondrial Ca2+ entry induce sustained inflammation, and MCU-mediated Ca2+ overload is essential for triggering NLRP3-mediated inflammation in patients with cystic fibrosis during infection with Pseudomonas aeruginosa." (PMID 32182899, 2020).
diffuse large B-cell lymphoma (1 paper, 2018). "These include EBV+ DLBCL, diffuse large B-cell lymphoma associated with chronic inflammation (DLBCL-CI), EBV+ MCU, FA-DLBCL, and LyG." (PMID 29518976, 2018).
energy metabolism disorder (1 paper, 2023). "We confirmed that the energy metabolism disorder of T2DM may be related to the mitochondrial dysfunction caused by the decreased expression of MCU and MICU1, and the abnormal mCa2+ uptake caused by the MCU-mediated mitochondrial dysfunction, which may be the pathogenesis of T2DM." (PMID 37337224, 2023).
fibrosis (1 paper, 2024). the formation of excess fibrous connective tissue in an organ or tissue in a reparative or reactive process. "Interestingly, fibroblast-specific deletion of MCU in adult mice induced myofibroblast formation, therefore leading to enhanced cardiac fibrosis." (PMID 39523398, 2024).
HCMV infection (1 paper, 2022). "It was observed that both total MCU protein and phosphorylated MCU protein were significantly increased after HCMV infection, and this increase was reversed after the addition of vitamin D3 and restored after exposure to AICAR or siVDR." (PMID 35359726, 2022). "HCMV infection not only upregulated YTHDF3 expression but also promoted its binding to MCU mRNA, and this interaction was significantly decreased after METTL3 knockdown." (PMID 35359726, 2022). "First, we investigated whether METTL3 or METTL14 (two m6A methyltransferases upregulated by HCMV infection) regulate MCU expression." (PMID 35359726, 2022). "HCMV infection induced a high percentage of apoptosis, which could be significantly reduced by MCU inhibition (Ru360 or siMCU) and further increased with spermine." (PMID 35359726, 2022). "Moreover, it was found that HCMV infection could promote vascular endothelial cell apoptosis by increasing MCU protein expression in an m6A-mediated pattern." (PMID 35359726, 2022). "YTHDF3 knockdown attenuated the MCU protein expression induced by HCMV infection but did not affect the MCU mRNA levels." (PMID 35359726, 2022). "It was also observed that ALKBH5 overexpression strongly reduced the increased levels of MCU protein induced by HCMV infection but did not affect the total MCU mRNA." (PMID 35359726, 2022). "In addition, knockdown of METTL3 in HCMV-infected HAECs similarly reduced the increase in protein expression of MCU induced by HCMV infection (mRNA expression was not affected)." (PMID 35359726, 2022). "However, silencing METTL3 but not METTL14 resulted in decreased MCU m6A methylation levels under HCMV infection conditions, suggesting that MCU mRNA may be subject to METTL3-dependent m6A methylation." (PMID 35359726, 2022). "Although our previous results showed that the expression of ALKBH5 and FTO did not change after HCMV infection, we still wondered whether ALKBH5 or FTO was involved in the HCMV-mediated m6A methylation of MCU mRNA." (PMID 35359726, 2022).
hepatitis C infection (1 paper, 2020). "In addition, high expression of MCU was associated with a high level of hepatitis C infection." (PMID 33114428, 2020).
hyperthyroidism (1 paper, 2025). Overactivity of the thyroid gland resulting in overproduction of thyroid hormone and increased metabolic rate. "We have previously demonstrated an increase in the levels of the channel-forming subunit MCU and cyclophilin D in an experimental model of hyperthyroidism." (PMID 41369368, 2025).
insulinoma (1 paper, 2013). "A recent report has shown that MCU silencing impairs insulin secretion stimulated from clonal rat insulinoma cells, INS-1(832/13), by 16 mM glucose." (PMID 23149488, 2013).
Iron overload (1 paper, 2024). "Iron overload caused cardiac mitochondrial dysfunction, as indicated by increased ROS production, mitochondrial membrane depolarization and mitochondrial swelling, and only the mitochondrial calcium uniporter completely protects against the cardiac mitochondrial dysfunction caused by iron overload." (PMID 38509409, 2024).
ischemic stroke (1 paper, 2018). A stroke disorder caused by obstruction of blood flow to the brain, due to thrombotic (local blood clot formation) or embolic (due to a blood clot or other material traveling from another site) event. "Based on these findings, we propose that brain-penetrant MCU inhibitors have strong potential to be well-tolerated and highly-efficacious neuroprotectants for the acute management of ischemic stroke." (PMID 29789575, 2018).
liver cancer (1 paper, 2020). An epithelial or non-epithelial malignant neoplasm that arises from the liver. "Analysis of the array expression database revealed that CREB1 has a strong binding site in the upstream promoter region of MCU and MICU2 in liver cancer (HepG2) cells." (PMID 33114428, 2020). "The mRNA levels of CREB, MCU, MICU1, and MICU2 were found to be significantly increased in liver cancer, indicating that these proteins may have potential carcinogenic effects." (PMID 33114428, 2020). "Next, we analyzed the endogenous levels of CREB, MCU, MICU1, and MICU2 in liver cancer cells and normal liver cell lines, and the results showed that the mRNA expression levels of CREB, MCU, MICU1, and MICU2 in liver cancer cell lines were higher than that in normal liver cells." (PMID 33114428, 2020).
liver fibrosis (1 paper, 2024). "Collectively, these results indicate that MCU-deficient mice strikingly limited MASH-associated liver fibrosis." (PMID 39523398, 2024). "Recent studies have demonstrated that MCU regulates the entry of Ca2+ into mitochondrial matrix that plays a key role in Ca2+ homeostasis, however, the precise role and potential mechanism of MCU in steatohepatitis and its related liver fibrosis waited to be elucidated." (PMID 39523398, 2024).
lung adenocarcinoma (1 paper, 2017). A carcinoma that arises from the lung and is characterized by the presence of malignant glandular epithelial cells. "To evaluate the possibility for clinical application, we tested the expression of DNAJB1, MCU, MPRIP, PSAP, RAI14, ZNF131 and TMC5 in 71 lung adenocarcinoma samples and paired adjacent normal tissue samples (>2 cm away from the tumor) from patients who underwent lobectomy or pneumonectomy." (PMID 29285248, 2017).
memory impairment (1 paper, 2020). "Other studies focused in brain function show that silencing of MCU during development induces memory impairment in Drosophila, and experiments in brain MCU-KO mitochondria revealed that MCU deletion did not completely block mitochondrial Ca2+ uptake, suggesting additional uptake pathways." (PMID 32967303, 2020).
metabolic dysfunction-associated steatohepatitis (1 paper, 2024). Metabolic dysfunction-associated steatohepatitis (MASH, formerly known as nonalcoholic steatohepatitis or NASH) is a type of fatty liver disease. "Mitochondrial calcium uniporter (MCU) plays pleiotropic roles in cellular physiology and pathology that contributes to a variety of diseases, but the role and potential mechanism of MCU in the pathogenesis of metabolic dysfunction-associated steatohepatitis (MASH) remain poorly understood." (PMID 39523398, 2024).
nonischemic cardiomyopathy (1 paper, 2021). Forms of cardiomyopathy that are not related to known coronary artery disease. "Under certain pathological conditions, such as nonischemic cardiomyopathy, MCU has been reported to dramatically upregulated, which may markedly increase the mitochondrial free Ca2+." (PMID 33493168, 2021).
oral squamous cell carcinoma (1 paper, 2025). "Dihydroartemisinin represses oral squamous cell carcinoma progression through downregulating mitochondrial calcium uniporter." (PMID 40539848, 2025). "Statement of Retraction: Dihydroartemisinin represses oral squamous cell carcinoma progression through downregulating mitochondrial calcium uniporter." (PMID 40539848, 2025).